CDH1 (cadherin 1)
Diseases named in the same sentence as CDH1 in open-access papers (continued):
Sharing a sentence is not in itself a finding about the gene and the disease.
lobular carcinomas (continued). "A prototype tumour with EMT is lobular carcinoma of the breast (LBC), which can be associated with sporadic or familiar defects in CDH1, the gene encoding for E-cad." (PMID 38201483, 2023). "In the present work, we reported that the CDH1 differential expression between ductal and lobular carcinomas was maintained in all examined 1,16 chromogroups that included a significant number of both histotypes." (PMID 33808143, 2021). "The higher frequency of CDH1 loss-of-function mutations and the lower transcriptional expression of the CHD1 gene in lobular carcinomas were some of the main differences between the two histotypes." (PMID 33808143, 2021). "Notably, germline CDH1 c.88C>A has been reported in lobular breast carcinoma and diffuse-type GC patients, as well as in two unrelated individuals with cleft lip with or without cleft palate, a developmental birth defect that is known to be overrepresented in CDH1 mutation carriers." (PMID 31600923, 2019). "In approximately 50% of lobular carcinomas loss of E-cadherin involves LOH at the chromosomal region of 16q, which includes the E-cadherin gene CDH1 locus and mutations in the remaining allele." (PMID 17437014, 2007). "CDH1 hypermethylation was observed in 72% of the cases including 52/71 ductal, 4/5 lobular carcinomas and 1 apocrine carcinoma." (PMID 16512896, 2006). "We confirmed the clear-cut difference in CDH1 expression between ductal and lobular carcinomas." (PMID 33808143, 2021). "In agreement with immunohistochemistry results, a previous analysis of TCGA data reported that CDH1 transcript and protein levels are significantly lower in lobular carcinomas compared to ductal ones, confirming that CDH1 expression differentiates the two histological subtypes." (PMID 33808143, 2021). "E-cadherin (CDH1 gene) germline mutations are associated with the development of diffuse gastric cancer in the context of the so-called hereditary diffuse gastric syndrome, and with an inherited predisposition of lobular breast carcinoma." (PMID 32560361, 2020). "On closer analysis, this is largely related to the lobular carcinomas within this IntClust; as would be expected, none of the tubular carcinomas in IntClust 3 harboured CDH1 mutations (OR 0.38 for tubular vs. 20.42 for lobular BC)." (PMID 29532008, 2018). "With respect to the molecular pathogenesis of HDGC, it is not surprising that the CDH1 mutation predisposes to malignancies with a dyshesive signet ring cell morphology such as diffuse gastric carcinoma and lobular breast carcinoma." (PMID 23849133, 2013). "Although CDH1 (E-cadherin), a classical member of the cadherin superfamily, was downregulated, THBS4 encoding calcium-binding adhesive glycoprotein, thrombospondin-4, was upregulated in all lobular carcinomas." (PMID 17389037, 2007). "Other studies have shown that mutations in α-catenin (encoded by the CTNNA1 gene), which forms the cadherin–catenin complex that is important for intercellular adhesion, may underlie the lobular carcinoma phenotype even in the absence of CDH1 mutations and the presence of normal CDH1 expression." (PMID 39201647, 2024). "However, NGS in this case revealed the hallmark loss of E-cadherin (CDH1, c.476del) within the lobular breast carcinoma (metastatic to the ovary) which was not identified within the uterine carcinosarcoma which makes it difficult to consider loss of CDH1 as a driver mutation for both tumors." (PMID 39076998, 2024). "Indeed, it has been repeatedly suggested that other mechanisms, such as epigenetic modifications, the upregulation of CDH1 transcriptional repressors, and other forms of transcriptional dysregulation, may account for the downregulation of CDH1 transcription in lobular carcinomas." (PMID 33808143, 2021). "Invasive lobular breast carcinoma was shown to be typically E-cadherin-negative and inactivating mutations has been frequently found along with LOH of the wild-type allele of CDH1." (PMID 30975222, 2019).
lobular carcinomas (continued). "HD of CDH1 was observed in 18 ductal/NST carcinomas (1.1%) and in 4 lobular carcinomas (2.1%)." (PMID 27161491, 2016). "Notably, ductal and lobular carcinomas have been observed in Pten+/−;Cdh1+/− compound mice (at approximately 30% incidence) at 6–7 months old, whereas no tumor has been observed in Pten+/− or Cdh1+/− animals at the same age." (PMID 31420536, 2019). "This confirms the hypothesis that non-pleomorphic lobular breast carcinoma can be considered as a low-grade subtype of ductal breast tumors; only the status of CDH1 expression is strongly different between the two types, which causes strong morphological differences." (PMID 20017941, 2009). "Several studies observed that some samples of prostate, bladder, endometrial, hereditary diffuse gastric cancer, and invasive ductal or lobular carcinoma did not contain a genetic change in CDH1, but showed a decrease in E-cadherin expression." (PMID 33915799, 2021).
lobular breast cancer (113 papers, 1999 to 2026). "Ultimately, CDH1 loss plays a central role in the development and progression of lobular breast cancer." (PMID 40757085, 2025). "Germline (likely-)pathogenic variants (PV) in CDH1 predispose carriers to hereditary diffuse gastric cancer and lobular breast cancer." (PMID 40323501, 2025). "Pathogenic variants of the CDH1 gene are involved in the predisposition to diffuse gastric cancer and lobular breast cancer." (PMID 41154377, 2025). "CDH1, encoding the cell adhesion protein E-cadherin, is a critical tumor suppressor gene frequently altered in lobular breast cancer (LBC)." (PMID 40757085, 2025). "It has been reported that CDH1 germline mutations are linked to hereditary diffuse gastric cancer and lobular breast cancer." (PMID 40236650, 2025). "Background/Objectives: CDH1 gene is widely studied, as pathogenic variants are involved in diffuse gastric cancers and lobular breast cancers." (PMID 41154377, 2025). "For instance, loss-of-function mutations in CDH1, which encodes E-cadherin, compromise epithelial integrity and promote invasion, predisposing individuals to hereditary diffuse gastric cancer and lobular breast cancer." (PMID 40759574, 2025). "Hereditary lobular breast cancer (HLBC) is a distinct subset of hereditary breast cancer primarily associated with germline pathogenic variants in the CDH1 gene, which encodes E-cadherin, a crucial protein in cell adhesion." (PMID 40366456, 2025). "Women with CDH1 mutations also face a 42–55% risk of lobular breast cancer, leading to a cumulative cancer risk of 90%." (PMID 39057027, 2024). "The lobular breast cancer metastatic to gynecologic organs demonstrated a pathogenic mutation in cadherin-1 (CDH1, c.476del, p.P159fs), which is a hallmark of ILC." (PMID 39076998, 2024). "CDH1 mutations also predispose individuals to lobular breast cancer and non-syndromic cleft lip and palate." (PMID 39057027, 2024). "In contrast, variants in CDH1 are uniquely associated with lobular breast cancer, particularly the invasive type." (PMID 38397209, 2024). "Pathogenic or likely pathogenic (P/LP) germline CDH1 variants are associated with risk for diffuse gastric cancer and lobular breast cancer (LBC) in the so-called hereditary diffuse gastric cancer (HDGC) syndrome." (PMID 38652475, 2024). "This cohort study examines the frequency of germline CDH1 sequence variations in women with the hereditary lobular breast cancer phenotype and the association of genetic profiles with clinical-pathological data and survival." (PMID 38652475, 2024). "A component of EMT is down‐regulation of E‐cadherin/CDH1, and inactivation of CDH1 is a driver mutation, for example in lobular breast cancer." (PMID 36811403, 2023). "Mutations in CDH1 (e-cadherin) are linked to autosomal dominant hereditary diffuse gastric cancer, as well as increased lobular breast cancer in female carriers." (PMID 36765680, 2023). "Noting that loss of CDH1 is the hallmark of lobular breast cancer, these authors also identified downregulated expression of CDH1 in MF/MC cancers." (PMID 37349265, 2023). "HDGC is characterized by autosomal dominant mutations in the CDH1 tumor suppressor gene (encoding the protein E-cadherin), leading to increased risks of diffuse gastric cancer and lobular breast cancer." (PMID 38136334, 2023). "The presence of the genomic mutation in CDH1 indicates that the evaluation of hereditary diffuse gastric cancer and lobular breast cancer should be considered when managing follow-up." (PMID 36768623, 2023). "Germline pathogenic variants in E-cadherin (CDH1) confer high risk of developing lobular breast cancer and diffuse gastric cancer (DGC)." (PMID 37761816, 2023). "CDH1 mutations, which are strongly associated with lobular breast cancer, were found less prevalent in the Vietnamese compared to the Caucasian, most likely due to the lower frequency of lobular cases at 1.5% in our cohort compared to 18.5% in the TCGA cohort." (PMID 36495126, 2023).
lobular breast cancer (continued). "Inactivating CDH1 mutations are found in 53% of lobular breast cancers in the literature and have higher median TMB than ductal tumors." (PMID 37637072, 2023). "Pathogenic and likely pathogenic (P/LP) germline variants in the tumor suppressor gene CDH1 (E-cadherin) result in increased lifetime risk of diffuse-type gastric cancer and lobular breast cancer." (PMID 36246616, 2022). "The first study addressing epigenetic inactivation of the CDH1 gene as a potential molecular mechanism for the loss of E-cadherin protein expression in the context of human lobular breast cancer appeared in 2001." (PMID 36139537, 2022). "Somatic CDH1 mutations have been identified in approximately 50% of sporadic diffuse gastric tumors and lobular breast cancers but rarely occur in other tumors." (PMID 35927682, 2022). "This rate of cleft lip/palate associated with germline CDH1 variants should be incorporated into considerations for genetic testing in patients with a personal or family history of diffuse gastric cancer or lobular breast cancer." (PMID 36246616, 2022). "Mutations of CDH1 (encoding E-cadherin) are characteristic of lobular breast cancer that shows single-file cancer cell growth." (PMID 35437329, 2022). "Recent studies have reported an association between CDH1 germline mutations and lobular breast cancer." (PMID 35805017, 2022). "CDH1 (E-Cadherin 1): Association of lobular breast cancer (LBC) is associated with germline pathogenic variants in CDH1, normally associated with hereditary diffuse gastric cancer (HDGC) and non-HDGC families." (PMID 34439109, 2021). "Inactivating mutations in the CDH1 gene cause the cancer syndrome hereditary diffuse gastric cancer and are also frequent in sporadic diffuse gastric and lobular breast cancers." (PMID 35008338, 2021). "The secondary cancer risk beyond lobular breast cancer has long been suspected, but establishing its incidence is limited by the rarity of CDH1 mutation prevalence." (PMID 34073553, 2021). "Carriers of CDH1 germline mutations have a high risk of developing diffuse gastric cancer and lobular breast cancer, associated with the cancer syndrome Hereditary Diffuse Gastric Cancer (HDGC)." (PMID 34503169, 2021). "Germline loss of the CDH1 gene is the primary genetic basis for hereditary diffuse gastric cancer, a disease resulting in elevated risk of both diffuse gastric cancer and lobular breast cancer." (PMID 35008266, 2021). "Patients with hereditary diffuse gastric cancer and lobular breast cancer with CDH1 mutations have a poorer prognosis." (PMID 34722557, 2021). "HDGC syndrome is caused by a mutation in CDH1, the gene encoding for the E-cadherin protein, and it is characterized by an association between signet ring cell/diffuse GC and lobular breast cancer." (PMID 33198203, 2020). "On the other hand, CDH1 germline mutations have been revealed to be capable of affecting hereditary lobular breast cancer as an independent-HDGC syndrome." (PMID 30975222, 2019). "While the association between mast cell gene expression and CDH1 mutation was as expected linked to lobular breast cancer, PIK3CA and MAP3K1 mutations were selectively associated with mast cell gene expression when considering only ductal carcinoma." (PMID 30993001, 2019). "In particular, the lifetime risk of developing hereditary diffuse gastric cancer (HDGC) and lobular breast cancer (LBC) in CDH1 mutation carriers has been estimated to be 80% and 60% respectively." (PMID 31028995, 2019). "It is known that CDH1 mutations can be found in patients with lobular breast cancer and in hereditary diffuse gastric cancer." (PMID 27696107, 2017). "Third, hereditary diffuse gastric cancer (HDGC, OMIM #137215) characterized by diffuse-type gastric cancer and an elevated risk of lobular breast cancer, which is caused by germline mutations of CDH1 coding for E-cadherin." (PMID 24373500, 2013).
lobular breast cancer (continued). "Germline mutations in CDH1 are well established as the defects underlying heredity diffuse gastric cancer (HDGC) syndrome along with an increased risk of lobular breast cancer (LBC) have been described in HGDC kindreds." (PMID 19584580, 2009). "In addition to DGC, female germline CDH1 mutation carriers have a lifetime risk of lobular breast cancer (LBC) estimated at 39–55%." (PMID 35406381, 2022). "The CDH1 mutation frequency affecting exclusively lobular breast cancer." (PMID 35563727, 2022). "However, among women diagnosed with bilateral lobular breast cancer prior to age 70, the yield of the detection of germline pathogenic CDH1 variants is 7%." (PMID 34771713, 2021). "Female CDH1 mutation carriers have additional risk of lobular breast cancer." (PMID 34073553, 2021). "In addition, we have established a murine-derived mammary organoid model of Cdh1 loss (manuscript in preparation) to provide models of lobular breast cancer in HDGC patients." (PMID 35008266, 2021). "Other authors propose that CDH1-associated hereditary lobular breast cancer may represent a distinct syndrome." (PMID 34771713, 2021). "Moreover, patients with CDH1 mutations are more at risk of diffuse gastric cancer and lobular breast cancer." (PMID 34818353, 2021). "Finally, these cells, having been derived from a patient with lobular breast cancer, have a point mutation in the CDH1 gene rendering them E-cadherin null, and thus, a good model of lobular breast cancer." (PMID 32715085, 2020). "Besides the role of E-cadherin in metastasis and invasion, CDH1 mutations were found in familial gastric cancer and lobular breast cancer." (PMID 32276436, 2020). "Interestingly, two tumors were diagnosed as lobular cancer and one had lobular features, in agreement with the increased prevalence of E-cadherin loss (encoded by CDH1) in lobular breast cancer." (PMID 24326041, 2013). "Some of this is explained by association with somatic genetic variants in genes TLX1 and CDH1; the latter is a known risk gene in hereditary diffuse gastric cancer and hereditary breast cancer, and it is tempting to speculate that NMD has a mediating role in this." (PMID 41023738, 2025). "The association between CDH1 gene mutation and lobular cancer has been well established previously, and it is not unrealistic to suggest that this CDH1 variant may be the cause of lobular breast cancer in this family." (PMID 28202063, 2017). "Despite progress in understanding the molecular role of CDH1 in lobular breast cancer, several gaps in research remain." (PMID 40757085, 2025). "Hereditary lobular breast cancer (HLBC) is a distinct form of hereditary breast cancer, primarily associated with germline pathogenic variants in the CDH1 gene, which encodes E-cadherin, a protein crucial for cell adhesion." (PMID 40366456, 2025). "Germline pathogenic variants and likely pathogenic variants (PV) in CDH1 predispose carriers to hereditary diffuse gastric cancer (HDGC) and lobular breast cancer." (PMID 40323501, 2025). "More broadly, several critical questions remain unanswered: What determines the tissue-specific manifestation of CDH1-related cancers—why some carriers develop lobular breast cancer, others diffuse gastric cancer, and some both?" (PMID 40366456, 2025). "Germline variants in CDH1 (E-cadherin) tumor suppressor protein are correlated with hereditary diffuse gastric cancer (HDGC) and a lifetime risk of 40–50% of developing lobular breast cancer." (PMID 38397209, 2024). "For instance, the role of the CDH1 gene in lobular breast cancer is well documented, while the FEN1 gene is associated with poor prognoses." (PMID 39335599, 2024).